FZD10 (frizzled class receptor 10)
Diseases named in the same sentence as FZD10 in open-access papers (continued):
Sharing a sentence is not in itself a finding about the gene and the disease.
cervical cancer (4 papers, 2016 to 2025). A primary or metastatic malignant neoplasm involving the cervix. "In vivo studies were conducted to demonstrate the potential of RIT when using FZD10 as a therapeutic target for cervical cancer." (PMID 40958973, 2025). "Because cervical cancer exhibits good radiosensitivity, the present study aimed to assess for prevalence of FZD10 in cervical cancer tissue and investigate the potential of 90Y-OTSA101 treatment for cervical cancer." (PMID 40958973, 2025). "Based on these findings, FZD10 was evaluated as a promising therapeutic target for cervical cancer.." (PMID 40958973, 2025). "In detail, we evaluated i) FZD10 expression in cervical cancer and other normal tissues as well as ii) the effect of 90Y-OTSA101 in vivo." (PMID 40958973, 2025). "The expression of FZD10 was evaluated via immunohistochemistry using formalin-fixed paraffin blocks collected from 84 patients with cervical cancer who underwent surgery." (PMID 40958973, 2025). "In this study, we evaluated i) the FZD10 expression in cervical cancer and ii) the effectiveness of 90Y-OTSA101 for cervical cancer." (PMID 40958973, 2025). "The present study demonstrated the great potential of targeting FZD10 for the treatment of cervical cancer." (PMID 40958973, 2025). "Because FZD10 expression was not strongly observed in normal tissues, except for the placenta, targeting FZD10 appeared to be a highly specific therapy for cervical cancer." (PMID 40958973, 2025). "This study found that FZD10 was strongly expressed in cervical cancer." (PMID 40958973, 2025). "However, in our analysis, FZD10 was strongly expressed even in early-stage cervical cancer and the cervix." (PMID 40958973, 2025). "This study aimed to evaluate FZD10 as a therapeutic target for cervical cancer." (PMID 40958973, 2025). "•・FZD10 is a potential target for cervical cancer treatment." (PMID 40958973, 2025). "Notably, FZD10-mRNA was reported to be highly expressed in cervical cancer cell lines." (PMID 40958973, 2025). "Furthermore, considering the expression of FZD10 in other tumor types, FZD10 may play a role in other tumor types like uterine corpus endometrial cancer and cervical cancer, which are treated with platinum-based chemotherapy often in combination with radiotherapy." (PMID 28641578, 2017). "FZD10 may be an appropriate target and 90Y-OTSA101 may have potential for the treatment of cervical cancer." (PMID 40958973, 2025). "FZD10 may be an appropriate target, and 90Y-OTSA101 may exhibit potential for the treatment of cervical cancer." (PMID 40958973, 2025).
colorectal tumors (4 papers, 2011 to 2019). "This contrasted with the observation that FZD10, a receptor for molecules in the Wnt pathway that is a good marker of colorectal tumors in humans, was the most upregulated GPCR in the PI of European sea bass." (PMID 27610085, 2016). "FZD10 is a positive regulator of the Wnt-βCatenin-TCF signalling pathway, has been shown to be up-regulated in primary colorectal tumours, and Wnt-beta Catenin signalling is known to be aberrant in some pancreatic adenocarcinomas." (PMID 21750719, 2011).
lung carcinoma (4 papers, 2011 to 2024). "FZD10 may play different roles in different types of cancers, and FZD10 methylation may be an early event in the development of lung cancer; both ideas are worthy of further study." (PMID 30286088, 2018).
cholangiocarcinoma (3 papers, 2019 to 2021). A carcinoma that arises from the intrahepatic biliary tree (intrahepatic cholangiocarcinoma) or from the junction, or adjacent to the junction, of the right and left hepatic ducts (hilar cholangiocarcinoma). "In a study, exosomal FZD10 protein and FZD10-mRNA were obtained from the culture medium of cellular lines of untreated colorectal, gastric and hepatic cancers and cholangiocarcinoma." (PMID 33669294, 2021).
renal cell carcinoma (3 papers, 2018 to 2020). "FZD10 can interact with HIG2 protein to enhance the activation of WNT/β-catenin signaling, which was involved in the growth of renal cell carcinoma." (PMID 33274190, 2020). "Hypoxia-inducible protein-2 (HIG2) was reported to bind to the extracellular domain of FZD10 and activated oncogenic WNT signaling in renal cell carcinoma (RCC)." (PMID 29789460, 2018).
pulmonary fibrosis (2 papers, 2018 to 2022). Chronic progressive interstitial lung disorder characterized by the replacement of the lung tissue by connective tissue, leading to progressive dyspnea, respiratory failure, or right heart failure. "Thus, our study identified Wnt/β-catenin signaling and hedgehog signaling crosstalk in pulmonary fibrosis in vitro and in vivo, and highlighted Gli1 and Fzd10 as a potential therapeutic target in pulmonary fibrosis." (PMID 29844390, 2018). "We further analyzed the effect of Fzd10 inhibition on BLM-induced pulmonary fibrosis." (PMID 29844390, 2018). "Targeted inhibition of Fzd10 could evidently suppress the development of pulmonary fibrosis." (PMID 29844390, 2018). "Moreover, FZD10 was upregulated and cross talked with TGF-β1, which activate the HH signaling pathway in myofibroblast differentiation and pulmonary fibrosis." (PMID 36776376, 2022). "Moreover, siRNA-mediated inhibition of Fzd10 prevented TGF-β1-induced myofibroblast differentiation of LR-MSCs in vitro and impaired bleomycin-induced pulmonary fibrosis." (PMID 29844390, 2018).
bone sarcoma (1 paper, 2015). A sarcoma that arises from the bone. "We found that FZD3, FZD5, FZD9 and FZD10 were prominently expressed in all bone sarcoma cells as compared to hMSC." (PMID 25999350, 2015).
deafness (1 paper, 2023). An inherited or acquired condition characterized by the complete loss of the ability to hear from one or both ears. "Defects in the 30 shared genes are related to several pathologies, such as vision abnormalities (TMEM135), cancer (CDH6, FZD10, TIAM2), neuropsychiatric disorders (Tenm4, Pde4dip, Grid2), deafness (TFB1M), neutrophil disorders (VPS45) and others." (PMID 36902345, 2023).
esophageal tumor (1 paper, 2021). "In esophageal stem cells, FZD10 expression is high, suggesting FZD10 may play a role in esophageal tumor initiation." (PMID 34604862, 2021).
gastrointestinal stromal tumor (1 paper, 2025). "For example, METTL3-mediated stabilization of USP13 RNA has been shown to promote autophagy and imatinib resistance in gastrointestinal stromal tumors, while in HCC, METTL3 has been reported to regulate cancer stem cell properties and contribute to lenvatinib resistance via FZD10." (PMID 39472692, 2025).
head and neck cancer (1 paper, 2022). A primary or metastatic malignant neoplasm affecting the head and neck. "The 499 patients with head and neck cancer were divided into two groups: those with low Fzd10 expression (n = 343) and those with high Fzd10 expression (n = 156)." (PMID 36776376, 2022). "As NPC is a distinct subtype of head and neck cancer, we evaluated the mRNA expression of FZD10 in head and neck cancer based on the Human Protein Atlas datasets and found that it is associated with the poor prognosis." (PMID 36776376, 2022).
osteosarcoma (1 paper, 2013). A usually aggressive malignant bone-forming mesenchymal neoplasm, predominantly affecting adolescents and young adults. "Furthermore, antibodies against Frizzled 10 (FZD10) may reduce osteosarcoma growth and metastasis." (PMID 23016862, 2013).
prostate tumors (1 paper, 2018). "FZD10 mRNA was only detected in VCaP cells, which express the highest level of Wnt-11, suggesting that FZD10 may be a functional Wnt-11 receptor in a subset of prostate tumors." (PMID 29717114, 2018). "However, FZD10 was not upregulated in prostate tumor datasets." (PMID 29717114, 2018).
renal carcinoma (1 paper, 2020). A carcinoma arising from the epithelium of the renal parenchyma or the renal pelvis. "Inhibited FZD10 expression via leflunomide treatment or RNAi targeting also caused suppression of renal cancer cell growth." (PMID 33274190, 2020).
serous ovarian cancer (1 paper, 2023). "For example, high FZD10, MKX, FAM83A and MYO18B methylation were related with response to platinum-based chemotherapy in advanced stage high-grade serous ovarian cancer (HGSOC), and these markers might be used to predict platinum sensitivity in HGSOC patients." (PMID 37732324, 2023).
cancer (41 papers, 2013 to 2025). A tumor composed of atypical neoplastic, often pleomorphic cells that invade other tissues. "MUC20, FZD10 have been identified in PC patients and these two genes play a vital role in two important pathways associated with cancer." (PMID 33240632, 2020). "In particular, Frizzled-10 (FZD-10) plays a role in gastrointestinal cancers and has been detected on the surface of exosomes derived from cells of these cancers." (PMID 38743146, 2024). "OTSA101, another humanized monoclonal antibody against Frizzled receptor 10 (FZD10), is labeled with yttrium-90 for targeted radiation delivery, selectively killing cancer cells expressing unnaturally high amounts of FZD10." (PMID 39123414, 2024). "There are many other cancer-related EVs that carry several molecules, including proteins such as vitronectin and integrin a/b, as well as lactadherin and frizzled class receptor 10 (FZD10)." (PMID 37958547, 2023). "Incubation with exogenous exosomes for 96 h restores the expression level of both pERK1/2 and Ki-67, suggesting a role of FZD10 in cancer cell proliferation via pERK1/2." (PMID 34671555, 2021). "While lncRNA regulation has yet to be described for both Fzd9 and Fzd10, the potential for investigation is clear as they have been shown to be differentially expressed during tumorigenesis in various cancers." (PMID 34671643, 2021). "Members in FZD family including FZD2, FZD4, FZD7, FZD8 and FZD10 have been demonstrated to mediate cancer cell epithelial-mesenchymal transition (EMT)." (PMID 33618713, 2021). "The involvement of FZD10 vehiculated in small extracellular vesicles (sEVs) in the control of cancer progression and cancer cell modification has also been suggested by another previous clinical study." (PMID 31935918, 2020). "Statistically, a significant increase of vimentin and FZD10 expression was recorded when HCEC-1CT cells were incubated with exosomes isolated by either the two cancer cell lines, at each investigated incubation time." (PMID 32933173, 2020). "The results of the present study seem to support the fundamental role of the Wnt cascade mediated by the FZD10 protein in carcinogenesis, as highlighted by the FZD10-mRNA silencing experiment performed on selected cancer cell lines." (PMID 31349740, 2019). "In particular, the presence of FZD10 and FZD10-mRNA in exosomes extracted from culture medium of the untreated colorectal, gastric, hepatic, and cholangio cancer cell lines, was detected." (PMID 31349740, 2019). "The study aimed to investigate the role of FZD10 on different cancer cell lines during the proliferation." (PMID 31349740, 2019). "We observed a correlation between cancer evolution and FZD-10 expression, and localization of protein during carcinogenesis." (PMID 29416658, 2018). "Another study reported that FZD10-mRNA delivering exosomes may be potential messengers of cancer reactivation and play an active role in long-distance metastasis." (PMID 40958973, 2025). "FZD10 may be an important cancer recurrent biomarker and a potentially effective target for cancer therapy." (PMID 36776376, 2022). "Our findings demonstrated that the FZD10, located in the metastatic cells and delivered by the secreted exosomes, plays a relevant role during the metastatic evolution, survival, and proliferation of cancer cells." (PMID 34671555, 2021). "Fzd1, Fzd2, Fzd6, Fzd9, and Fzd10 currently do not have any circRNA molecules associated with regulation of their expression, despite their obvious role in cancer signaling and tumor progression, highlighting the potential for future research." (PMID 34671643, 2021). "The immunofluorescence analysis shows a significant increase of fluorescence intensity index (p < 0.001 versus control cells) of vimentin and FZD10 upon exposure of HCEC-1CT cells to exosomes derived from both the two cancer cell lines, at each investigated incubation time." (PMID 32933173, 2020).
cancer (continued). "We focused on FZD10 because, as a receptor for the canonical Wnt pathway, it is known to enhance oncogenic Wnt signaling as well as to regulate cell function in different cancers." (PMID 32138771, 2020). "Global relative expression of FZD10 in different types of cancer based on the TCGA data." (PMID 28641578, 2017). "FZD10 has been described as a functionally relevant WNT pathway receptor in several cancer types." (PMID 28641578, 2017). "Another source of resistance stems from the presence of cancer stem cells, where METTL3 enhances drug resistance through Frizzled Class Receptor 10 (FZD10) in these cells." (PMID 40103332, 2025). "Previous studies have determined a direct role for the SS18-SSX fusion protein in regulating expression of several cancer-related genes, such as EGR1, FOS, IGF2, FZD10, SOX2, UNCX and CDH4." (PMID 39045458, 2024). "Relatively, FZD10 and TCF4 were highly expressed in these para-carcinoma tissues but significantly reduced in the core carcinoma tissues." (PMID 32273945, 2020). "The study also indicated that cancer cells that were immune-positive for FZD10 displayed less nuclear accumulation of β-catenin, suggesting that FZD10 functions via the non-canonical pathway." (PMID 40869407, 2025). "In HCC cancer stem cells (CSCs), methyltransferase 3, N6-adenosine-methyltransferase complex catalytic subunit (METTL3)-mediated m6A modification of Frizzled-10 (FZD10) mRNA resulted in FZD10 upregulation." (PMID 39682130, 2024). "FZD10, a Wnt signaling receptor, is involved in NPC recurrence, and could serve as an independent predictive biomarker for cancer recurrence." (PMID 36776376, 2022). "Treatment of FZD10‐silenced cells with Exos of nonsilenced cells reinstated viability, and the Fzd10 protein and mRNA levels indicate its function for cancer reactivation and long‐distance metastasis." (PMID 33207034, 2021). "Furthermore, we have reported a study performed on tissues of three different cancers, namely CRC, melanoma and gastric cancer, demonstrating a strong correlation between the expression levels of FZD10 and different tumor stages." (PMID 32664186, 2020). "Nevertheless, analysis in human cancer cells demonstrates the promotion of cell motility through activation of the non-canonical pathway by FZD10." (PMID 23349976, 2013). "Ligands such as Tumor Necrosis Factor-Related Apoptosis-Inducing Ligand (TRAIL), Frizzled 10 (FZD10) Protein, EpCAM Aptamer, Programmed Cell Death Protein 1 (PD-1), RGD, CC-9 and RH-20, and specific DNA sequences have demonstrated enhanced uptake by cancer cells and cytotoxicity." (PMID 38543324, 2024). "To date, there has been no report on the role of FZD10 in the recurrent cancers." (PMID 36776376, 2022). "Interestingly, their study indicated that FZD10 was expressed only in cancer cells and it was absent in adjacent normal cells." (PMID 32664186, 2020). "FZD10 has been reported to be specifically localized in the exosomes of CRC and GC patients, indicating that this protein may play a crucial biological role in human cancers of the gastrointestinal tract and may be a potential biomarker in the management of CRC and GC." (PMID 34671555, 2021).
tumor (31 papers, 2010 to 2025). "Conversely, FZD10 exhibited relatively low expression in TC/TE in Patients 13 and 18, progressively increasing in the direction away from the tumor." (PMID 41184502, 2025). "For example, antibodies targeting the extracellular domain of FZD5, FZD7, and FZD10 have been successfully applied to inhibit the individual FZD-induced tumor growth in pancreatic ductal adenocarcinoma, Wilms’ tumor, and synovial sarcoma, respectively." (PMID 36620565, 2022). "In fact, LINC00473 and FZD10 were identified previously as being associated with FLC-specific super enhancers, which are known to mark genes that are critical for tumor cell behavior." (PMID 35167623, 2022). "In this context, our previous study, performed on tissues of patients affected by CRC and GC, highlighted a strong correlation between the expression level and cell localization of FZD10, occurring as a function of different tumor stages." (PMID 34671555, 2021). "The estimated biodistribution and dosimetry of (radio)labeled anti-FZD10, in normal tissue and tumor, was evaluated through Monte Carlo-based 3D simulations." (PMID 34440182, 2021). "To further investigate the role of FZD10 on tumor proliferation, we silenced FZD10 in SW620 and N87, CRC and GC cells, respectively, and analyzed pERK1/2 and Ki-67 expression by confocal microscopy investigation before and after cell treatment with exosomes." (PMID 34671555, 2021). "The overall results suggest that FZD10, delivered by circulating tumor-derived exosomes, can play a relevant role in promoting the CRC carcinogenesis and propagation." (PMID 32933173, 2020). "The semi-quantitative analysis proved an expression level of FZD10 in the tumor-derived exosomes significantly (p < 0.001 versus normal cells) higher than in the exosomes extracted from HCEC-1CT cell line." (PMID 32933173, 2020). "The tumor-derived exosomes were characterized by significantly enhanced expression level of FZD10 compared to the exosomes derived from the normal cells." (PMID 32933173, 2020). "In summary, promoter hypermethylation downregulates SEPT9_v2, which acts as a NPC tumor suppressor through inactivation of the Wnt/β-catenin signaling pathway via miR92b-3p/FZD10." (PMID 32138771, 2020). "Evidence of a possible tumor biological role of the FZD-10 includes the upregulation of FZD-10 mRNA in several types of human cells during the carcinogenesis through activation of the β-catenin-TCF signaling pathway, in presence of Wnt." (PMID 31275379, 2019). "Another hurdle encountered during the preparation and conduct of this study, was the lack of validated immunohistochemistry (IHC) assay to assess FZD10 expression on tumor cells." (PMID 29884132, 2018). "The nuclear expression of FZD-10 or its absence can give a new tool for tumor staging to pathologists." (PMID 29416658, 2018). "Our findings indicate an important role of FZD-10 in tumor progression especially in the later stages of tumor." (PMID 29416658, 2018). "In colon cancer, the cytoplasmic staining of FZD10 increases as the tumor progress." (PMID 36620565, 2022). "Interestingly, an essential role of FZD10, that is an active receptor involved in the Wnt signal and delivered by exosomes, in the triggering the activation of the entire tumor cascade in normal cells, can be reasonably expected." (PMID 32933173, 2020). "In this perspective further investigation could be performed to monitor cell morphological variations, to assess the paracrine control of the Wnt cascade mediated by extravesicular FZD-10, on the remodeling of tumor cells." (PMID 31275379, 2019). "Here we observed a decrease of FZD-10 in the cytoplasm with increasing malignancy of the tumor." (PMID 29416658, 2018). "Some bulky tumors demonstrated heterogeneous tracer uptake as a result of the various tumors vascularizations, tumor necrosis depending on tumor size, the capacity of the antibody to diffuse into the tumors, the expression of FZD10, the antibody internalization." (PMID 29884132, 2018).